KLRC4-KLRK1 (KLRC4-KLRK1 readthrough)
Gene: Protein-coding gene on chromosome 12 (10,372,353 to 10,410,146, reverse strand). Ensembl gene ENSG00000255819.
Genetic constraint (gnomAD): Missense variants: 124 observed, 157.41 expected, observed/expected ratio (o/e) 0.79, 90% interval 0.68 to 0.91. Synonymous variants: 41 observed, 50.6 expected, observed/expected ratio (o/e) 0.81, 90% interval 0.63 to 1.05.